IL1B (interleukin 1 beta)
Diseases named in the same sentence as IL1B in open-access papers (continued):
Sharing a sentence is not in itself a finding about the gene and the disease.
infection (continued). "BARM showed a more inhibitory effect compared to the control at 18 h post-infection with IL-6 and IL-8 but not for IL-1β." (PMID 36992362, 2023). "Notably, the levels of IL-1β, IL-6, and TNF-α were significantly elevated following infection with B1033 compared with those in the wild-type (p < 0.001)." (PMID 37998345, 2023). "Likewise, IL-1β production was also detected after WT MeV and LAMV infection of parental M0, M1 and M2 THP-1 cells further indicating inflammasome induction by WT MeV and LAMV of both inflammatory and anti-inflammatory THP-1 macrophages." (PMID 36851476, 2023). "Levels of proinflammatory chemokines and cytokines CXCL1, CCL5, IFN-γ, IL-1β, CXCL10, IL-17, TNF-α and IL-6 were also assessed in the brain, spleen and liver of MAYV-infected mice throughout the infection." (PMID 36902230, 2023). "Another report suggests that infection induces neutrophils pyroptosis via ATP-mediated P2X7R signaling, resulting in cytoplasmic low K+ activation of NLRP3 inflammasome together with mature IL-1β and IL-18 release." (PMID 37063905, 2023). "Furthermore, the infection also encourages macrophages to secrete pro- and anti-inflammatory cytokines such as tumor necrosis factor-α (TNF-α), interleukin-1β (IL-1β), IL-6, interferon-γ (IFN-γ) and IL-10." (PMID 37280772, 2023). "Early in infection, the infected cells are activated and start to release some early mediators of inflammation such as TNF-α, IL-1α, IL-1β, IFN-γ and chemo-attractant molecules (e.g. CXCL5, CXCL8), some of which also characterize the early stages of SARS-CoV-2 infection." (PMID 37662901, 2023). "We also observed significant abrogation of IL-1α and IL-1β release in the absence of gasdermins D and E following infection during TNF priming, indicating that TNF licenses cells to undergo gasdermin-mediated pyroptosis to release IL-1 cytokines." (PMID 37279255, 2023). "IL1β, an important agonist of the IL1 family, is a multifunctional cytokine, which is crucial for activating neutrophils and macrophages to clear invading pathogens, thereby serving as a vital component of host defense against infection." (PMID 37799603, 2023). "Infection with the H7N7 resulted in increased levels of CCL2, IFNγ, IL1β, IL-6, and TNFα in the brains of mice, whether or not they had been previously vaccinated." (PMID 37063291, 2023). "By contrast, cells that were pretreated with chloroquine before infection exhibited trends towards decreasing levels of proinflammatory TNF-α, IL-6 and IFN-γ, and increasing levels of IL-1β, compared with untreated cells infected with Mel+ or Mel˗ S. globosa conidia." (PMID 37141335, 2023). "In addition, although the transcription of various cytokines, such as IL-1β, IL-2, IL-4, IL-8, and IL-10, was shown to be highly upregulated to defend the organism against DHAV-(1/3) infection, the variation of duck IL-22 after DHAV infection is still unclear." (PMID 37391858, 2023). "As the first line of defense of the lung, the airway epithelium provides a physical barrier to prevent infection but also produces chemokines and cytokines such as TNF-α, IL-1β, IL-6, IL-8, and IL-12 that are important mediators in both lung defense and inflammation." (PMID 38102682, 2023). "Results from our experiments with treatment of BMDMs with CA and ∆yopK Yptb mutant infection showed that there was a nonsignificant decrease in IL-1β release which can be attributed to the inhibition of NLRP3 but not of the NLRC4 inflammasome." (PMID 37787552, 2023). "However, even given this limitation, clear trends were observed, with increases in the pro-inflammatory cytokines TNFα and IL-1β, the regulatory cytokine IL-1RA and the chemokines CCL2, CCL17 and CCL3 in the sputum post-infection." (PMID 37012228, 2023). "GO analysis of the infection genes upregulated at one week indicated processes involved in immune responses and cytokine production, including responses to interferon-gamma and positive regulation of TNF, IL6, and IL1β production." (PMID 37200402, 2023).
infection (continued). "In addition, serum levels of IL6 and IL1β were elevated in patients with PASC and consistently higher than in children who recovered from infection." (PMID 36674665, 2023). "In fact, NET formation can also be induced by several immune factors independent of an infection, e.g., by the proinflammatory mediators interleukin (IL)-8 and IL-1β, autoantibody overexpression, or activated platelets." (PMID 38169647, 2023). "Plasma cytokines (IL-1β, IL-3, IL-6, IL-8, IL-18, IP-10, MIG, TNF-α, IFN-γ, MIP-1α and MIP-1β) and total peroxide (TPX) levels were quantified at baseline and at months 1 and 6 after the onset of the infection." (PMID 37894054, 2023). "In response to infection, four interleukins (IL1A, IL1B, IL8 and IL16), their receptors (IL1 receptor like 1, IL1 receptor 2, IFN-lambda receptor 1, cytokine receptor like factor 1) and two acute phase proteins (Serum amyloid A 1 and 2) were differentially expressed." (PMID 38179419, 2023). "Our data suggest that BM CD63+ stromal cells contribute to inflammation with Il1b expression in the absence of IL-1rn with no need of injury or infection sensing." (PMID 36596811, 2023). "Similarly, at 12 h post infection, C1q-treated cells exhibited lower gene expression levels of IL-6 (~ −5-fold), IFN-α (~−1.9-fold), IL-1β (~−4.5-fold), and TNF-α (~−4.4-fold)." (PMID 37376569, 2023). "Furthermore, these two PRRSV strains elicited divergent cytokine responses, such that SD53-1603 infection induced higher levels of TNF-α and IFN-γ, whereas HuN4 infection upregulated IL-1β." (PMID 37920268, 2023). "Whole lung tissue was collected 24 h after infection and processed for RT-qPCR to evaluate for relative gene expression of proinflammatory genes IRAK1, TRAF6, NF-κB, IL-6, MIP-2 (murine IL-8 analog), IL-1β, and TNFα as these cytokines outline the pathway along which miR146a functions." (PMID 37765178, 2023). "IL-1β was not significantly affected following infection in either sex at any time point or at baseline." (PMID 37737732, 2023). "The results showed that the concentration of IL-1β in LPS-primed PAMs increased with increasing MOI and prolonged infection duration, which confirmed that PRRSV could activate the inflammatory corpuscle signal and nuclear factor κB (NF-κB) in PAMs." (PMID 37256059, 2023). "Surprisingly, expressing clsB in trans was not sufficient to restore the macrophage infection and IL-1β secretion phenotypes of the ΔclsAB-, ΔclsBC-, or ΔclsABC-mutant S. Typhimurium." (PMID 35638781, 2022). "It reduces the production of pro-inflammatory factors such as interleukin (IL)-1β and tumor necrosis factor (TNF)-α and increases the production of the anti-inflammatory cytokine IL-10, which results in immunosuppression and worsening of infection." (PMID 36556017, 2022). "The AAV9-SLPI infection has significantly reduced inflammatory cytokine levels when compared with AAV9 group (TNF-α: 85.92 ± 36.24 ng/mg vs. 186.1 ± 12.17 ng/mg, p < 0.05, IL-1β: 29.48 ± 4.20 ng/mg vs. 69.03 ± 9.17 ng/mg, p < 0.05, and IL-6: 74.23 ± 10.50 ng/mg vs. 113.1 ± 28.43 ng/mg, p < 0.05)." (PMID 36061560, 2022). "Since the outcome of infection in the constitutive absence of IL-1R reflect the role of IL-1β in the generation of CCC, which based on our results, seems to be of little relevance, we performed IL-1R blockade in infected WT mice." (PMID 36341442, 2022). "As in the case of TNF-α, the ΔpyrC mutant strain-infected U937 cells showed significantly higher levels of IL-1β and IFN-β production than the wild-type strain, and pyrC complementation decreased these levels to that observed upon infection with the wild-type strain." (PMID 36389167, 2022). "Heightened colonic cytokine levels in the WT-infected group also correlated with significant increases in serum GCSF, IL-1β, IL-3, IL-6, IL-17, CXCL1, CXCL9, MCP-1, TNF-α and TREM at the peak of infection (48-hours), when compared to the TcdA−TcdB−CDT+ and uninfected groups (p< .05)." (PMID 36045589, 2022).
infection (continued). "The IL-1β secretion was mainly negative or very poor in response to infection by NEW1, CAS, and Beijing genotypes and mock cells." (PMID 36000264, 2022). "During the initial steps of infections with MEL and MSL, mycobacteria were able to evade the oxidative mechanisms of the innate immune response (ROS production by macrophages) and stimulate a pro-inflammatory environment (TNF-α, IL-1β, and IL-8)." (PMID 35873160, 2022). "At 7th day post challenge, TLR5, TLR7, il6, il1b, and IL12B were still highly expressed, suggesting that TLR may play a role in both early and late stages of infection." (PMID 36439120, 2022). "Upon the infection of RSV (strain A2) in primary human lung epithelial cells, the knocking down of TLR4, but not TLR3, TLR7, TLR8, or RIG-I results in a reduced expression of pro-IL-1β and IL-1β." (PMID 35308390, 2022). "Additionally, after infection with three PRV strains, the transcriptional levels of IL-1β, IL-6, TNF-α, and IFN-β were highest at 3 h, 6 h, 9 h, and 12 h, respectively, and then gradually decreased." (PMID 35458442, 2022). "Furthermore, the induction of IL-6, IL-23, IL-1β and TNFα by IL-17 constitutes a positive feedback loop that enhances their production by Th17 cells production and strengthens the effects of IL-17 which may form the basis of a self-sustaining process for IL-17 secretion during infection." (PMID 36136963, 2022). "Moreover, SEP attenuated the MPO level in the lung and inflammatory cytokines IL-1β, TNF-α, IL-6 in the peritoneal macrophage during infection." (PMID 35370674, 2022). "Our previous study has shown that IL-1β and S1PR1 gene expression levels are significantly increased in SPF chickens and DF-1 cells following infection with GM; S1PR1 overexpression could increase the gene expression of IL-1β induced by NDV." (PMID 35854395, 2022). "Although NLRC4 mediates IL-1β secretion following infection with other Gram-negative pathogens, we consider it unlikely that KP activates NLRC4 because KP does not express any of the bacterial proteins known to activate this inflammasome." (PMID 35947948, 2022). "In the present study, the mRNA levels of IL-6, IL-1β and IFN-α in LMH cells -infected with FAdV-4 co-treatment with 300 μg/mL arginine medium were significantly relieved (P < 0.05), compared with FAdV-4 infection cells." (PMID 35590365, 2022). "Similarly, inhibiting the expression of miR-126-5p infection with NDV significantly promoted the expression of IFNβ, PKR, MX1, IL-1β, IL-6, and IL-8." (PMID 36224663, 2022). "Both at 6 and 24 h after infection, bacterial burdens, neutrophil recruitment, neutrophil activation (CD11b expression, MPO and elastase production in the BALF), and pro-inflammatory cytokines (IL-1β, IL-6 and TNF) levels were similar in both mouse strains." (PMID 35269409, 2022). "Similarly, the expression of GLUT1, MCT4, NLRP3, and the mature form of IL‐1β increased in the setting of MRSA, HK‐MRSA, and VT‐MRSA infection (Fig EV1B)." (PMID 36354099, 2022). "Initially, we and other groups observed no or low levels of IL-1β in the lungs of K18-hACE2 mice over the course of infection with the wild-type strain (2.4 × 104 to 1 × 105 PFU)." (PMID 36005818, 2022). "Increases in maternal levels of IL-6, IL-1β, TNF-α, and IFN-β in response to infection can damage the placenta and intrauterine fetal growth restriction caused by hypoxia that can be detected as upregulation of hypoxic-inducible factor-1α (HIF-1α) in the placenta." (PMID 35464419, 2022). "Thus, IL-1β and TNF-α, as stress-inducible genes, are consistently upregulated in expression during infection." (PMID 36139883, 2022). "In addition, aged ferrets showed high expression of chemokines (CCL4 and CXCL10) and inflammatory cytokines (IFNB1, IL1B, IL6, and IL7) in the early phase of infection." (PMID 35013229, 2022).
infection (continued). "In addition, infection by SARS-CoV-2 increases glycolytic activity and the expression of inflammatory genes such as TNF-α, IL-6, IL-1β, INF-α and INF-β, and this inflammatory response is potentially harmful to renal tissue." (PMID 36439786, 2022). "In our study there was an important increase in pro-inflammatory cytokines (IL1β, IL6, TNFα, IL18, IL23) upon infection in all the groups analyzed in comparison with age-related control samples, as also seen for the immunoregulatory cytokines IL10 and IL17A, and for Th1 IFNγ NLF." (PMID 36561744, 2022). "Meanwhile, we also found UGRP1 slightly increased mRNA levels of Il6, Il1b and Tnfa in PEMs without infection of S. pneumoniae." (PMID 35652821, 2022). "The studies prompted us to investigate the secretion of IL-1β and IL-18 after SEZ infection." (PMID 36311722, 2022). "The results showed that the transcription levels of pro-IL-1β in the BAY11-7082-treated PAMs were decreased by 2.75- and 2.65-fold at 12 and 24 h, respectively, compared with those in the medium-treated PAMs upon ASFV-ΔH240R infection." (PMID 36326277, 2022). "In addition, the infection by SARS-CoV-2 triggers the inflammasome in macrophages, leading to IL-1β and IL-18 release in the lungs and contributing to pulmonary inflammation." (PMID 36083891, 2022). "Under SPI-II inducing conditions, the NLRC4 inflammasome only contributed significantly toward IL-1β secretion, and its ablation did not significantly protect against the induction of cell death after infection." (PMID 34864057, 2022). "We found that IL-1β was highly expressed in the spleen and bursa of chickens at 7 and 14 after MDV/CVI988 infection, and the expression level gradually decreased with time, which was consistent with the data reported previously on N2a strain chickens infected with the MDV JM-6 strain." (PMID 36680047, 2022). "For instance, ST infection could recruit the inflammatory monocytes to the CNS in mice; Salmonella-derived LPS markedly activated the expression of TNF-α, IL-1β, and IL-6 in microglia and astrocytes in vitro." (PMID 35967771, 2022). "LPS along with Nigericin or SVA infection could induce IL-1β secretion and IL-1β maturation, but VX-765 (Casp-1 inhibitor) inhibited SVA-induced IL-1β production." (PMID 35254168, 2022). "Notably, we found that the expression of specific markers of M1 type microglia (Aif1, Cd86, Cd40, Ccl2, Ccr2, Cx3cr1, IL-1β, IL-6, and NOS2) was elevated post infection." (PMID 36618398, 2022). "Infection resulted in increased expression of il1b and tnfb1b in both bcl6aawt/wt and bcl6aamdu21/mdu21 embryos (data not shown), but il1b was significantly enhanced in bcl6aamdu21/mdu21 compared to bcl6aawt/wt embryos." (PMID 36389136, 2022). "Furthermore, ECHO 11 infection triggered NLRP3 inflammasome activation, as evidenced by cleavages of GSDMD, pro-IL-1β and pro-caspase-1, and the release of LDH." (PMID 36026486, 2022). "ZIKV (H/PF/2013) infection of microglial cells resulted in the expression of high levels of interferon type I (IFN-α and IFN-β) and type II (IFN-γ), as well as neurotoxic factors with strong proinflammatory effects (TNF-α, IL-1β, IL-6, MCP-1)." (PMID 35371036, 2022). "IL-1β, TNF-α, IFN-γ, and IL-6 plasma levels were measured on d2, d4, d6, and d8 post-infection." (PMID 36456548, 2022). "Infection-induced OXSR1 may suppress protective NLRP3 inflammasome responses and downstream IL-1β/TNF-α production." (PMID 35545295, 2022). "While IL-1β and TNF-α levels may drop within 24–48 h, elevated IL-6 levels persist for a longer period over the course of the infection." (PMID 35888173, 2022). "Moreover, we found that the protein levels of IL1B, IL6, and TNF showed a significant and time-dependent increase accompanying infection." (PMID 35794518, 2022).
infection (continued). "Infection (NC group) with E. maxima increased the gene expression of TNFSF15 (p = 0.006, 2.9 × 10−3 to 2.3 × 10−2), IL-1β (p = 0.001, 1.9 × 10−3 to 4.9 × 10−3), and IL-8 (p = 0.022 6.3 × 10−3 to 2.0 × 10−2) in the distal jejunum compared to that of the CON group." (PMID 35812452, 2022). "TNF-α, IL-1β, VEGFA, and ICAM-1 mRNA levels in tissues were detected, which were observed to be remarkably upregulated in the DR and DR + Lv-sh-NC groups whereas partially downregulated after Lv-sh-Cx43 infection." (PMID 36120455, 2022). "In addition, corneas of mice were collected 5 days after infection to detect the RNA and protein levels of neutrophil chemokine CXCL1 and IL-1β." (PMID 35437453, 2022). "In addition, using a high concentration of Ca2+ facilitates IL-1β secretion, which was induced by SVA infection or 3D expression but reversed the results with K+." (PMID 35254168, 2022). "The immediate response to infection and/or tissue damage involves liver production of acute phase proteins like C-reactive protein (CRP) and serum amyloid A (SAA); fever, often triggered by the pyrogenic cytokine IL-1β; and granulocytosis." (PMID 35821823, 2022). "Therefore, hiNeurons and hiAstrocytes were infected with Tha-eGFP or Th2P-4M-eGFP and treated with human recombinant IL-1β, IL-6, or LIF two hours after infection." (PMID 36680128, 2022). "During the early phase of infection of bovine MDMs, C. burnetii induces a marked increase in IL-1β mRNA but fails to increase mature bioactive IL-1β." (PMID 36558755, 2022). "Additionally, RGS2 expression was strongly correlated with PTGS2, IL1B, CXCL8, NAMPT and other inflammation markers with substantial upregulation in early infection." (PMID 36143181, 2022). "Activation of these transcription factors may lead to expression of various cytokines genes such as IL1B, CXCL2 and CXCL3, which in turn recruits immune cells to the site of infection." (PMID 37193047, 2022). "As a result, we observed that MyD88 -/- monocytes failed to induce IL-1β after infection with L. corymbifera in contrast to WT monocytes." (PMID 36311802, 2022). "Venn diagram analysis showed that among the common DGEs in the 3 h and 12 h infection groups compared with the control group, 11 differential genes were enriched in the NF-κB signaling pathway, including CXCL8, IL-1β, CCL4, IκBα, TNF, NF-κB, CFLAR, PTGS2, TRAF1, PLAU, and IL-1β2." (PMID 35215890, 2022). "We examined the expression of IL-1β, IL-6 and TNF-α after infection with S. aureus." (PMID 35624447, 2022). "In Thio-Pmacs, we found that inhibition of C3aR did not affect TNFα or IL-1β secretion, but slightly inhibited IL-6 secretion at 2h, but not 6h post-infection." (PMID 36174103, 2022). "However, other proteins such as ISG15, Nitric Oxide Synthase 2 (NOS2), IL1-β and IFIT1 were similarly altered in both conditions upon infection." (PMID 36131943, 2022). "Other studies have found that sublytic stimulations, such as infections with mutant S. aureus, may cleave GSDMD for IL-1β secretion below the limit of detection by immunoblot." (PMID 35832789, 2022). "This was associated with the decreased expression in mRNA of BDNF, NGF, and FGF2, and elevated expression of IL-1β in the hippocampus at 6 h post infection, but with no changes in optical intensity of the microglia and astrocytes." (PMID 35741412, 2022). "However, the expression levels of IL-1β and IL-6 were decreased by SP600125 treatment in monocytes or macrophages in the presence of CHa strain infection." (PMID 35837399, 2022). "Cytokines such as IL‐1β, IL‐6 and TNF‐α are important in eliminating infection." (PMID 35502484, 2022). "When microglial cells face a pathogen, for instance Streptococcus pneumoniae, a microorganism whose infections produce meningitis, they respond by assembling inflammasome NLRP3, activating caspase-1, secreting IL-1β and IL-18 and inducing cell death by pyroptosis." (PMID 35783102, 2022).